BIRC5 (baculoviral IAP repeat containing 5)
Diseases named in the same sentence as BIRC5 in open-access papers (continued):
Sharing a sentence is not in itself a finding about the gene and the disease.
cancer (continued). "Three pathways demonstrated top priorities, and the one with specific associations with cancers, ‘pathways in cancer,’ was analyzed with its four highlighted genes, namely, BIRC5, E2F1, CCNE1, and CDKN2A, which were validated using Oncomine." (PMID 28316892, 2017). "BIRC5 encodes the expression of anti-apoptotic protein survivin and elevated activity of this survival cascade has been implicated in cancer cell survival and disease progression." (PMID 28582447, 2017). "Survivin (also known as BIRC5) is a cancer-associated protein that inhibits cell death and is essential for mitosis." (PMID 27246243, 2016). "Survivin (also known as BIRC5) is a cancer-associated protein that exists in several locations in the cell." (PMID 27246243, 2016). "Genes associated with the actions of miR-203 in other cancers, such as BIRC5, SNAI2, P63, and c-Jun, were not enriched in our samples." (PMID 25284788, 2014). "For instance, the anti-apoptotic proteins SOCS3, BCL2, and BIRC5 are known to be implicated in a number of cancers and to contain putative miR-203 binding sites within their 3'UTRs." (PMID 25004126, 2014). "Many studies using clinical specimens have shown that BIRC5 is invariably overexpressed in a majority of human cancers and is linked to poor patient prognosis but is rarely expressed in normal tissues." (PMID 23433354, 2013). "The protein Survivin is encoded by BIRC5 (located in 17q25) and is well-known for its role in mitotic regulation and apoptosis, and has been developed as a target for cancer treatment." (PMID 21806811, 2011). "Previous studies have reported that the BIRC5 -31C/G polymorphism was associated with invasiveness or metastasis of some types of cancer." (PMID 21304814, 2011). "While this study confirms BIRC5’s critical role in cancer progression and highlights its diagnostic and prognostic potential, further research is necessary to validate these findings and uncover the precise mechanisms by which BIRC5 operates." (PMID 39703228, 2024). "Thus, overexpression of BIRC5 caused cancer-promoting effects in the three types of RCC cells and normal kidney cells." (PMID 38203388, 2023). "BIRC5, a suppressor of apoptosis encoding the protein Survivin, is a mitotic spindle checkpoint gene located on chromosome 17 that is overexpressed in most cancer cells and its high expression is associated with worse survival." (PMID 37834111, 2023). "In addition to TEAD family members, TBX5 is known to be correlated with YAP1 by forming a complex with YAP and β‐Catenin in initiating the expression of BIRC5 that encodes Survivin and is crucial for cancer cell survival." (PMID 35000271, 2022). "Moreover, BIRC5 is highly expressed in tumors, including cancer cells and tumor stem cells, whose expression is associated with the differentiation, proliferation, invasion and metastasis of tumor cells." (PMID 34330893, 2021). "We found that BIRC5 expression levels correlated with methyltransferase expression levels in different types of tumors, and the association between immune checkpoints and BIRC5 in cancer shows its potential as a therapeutic target." (PMID 33431968, 2021). "Overexpression of BIRC5 proteins in various cancers is associated with poor survival." (PMID 34484469, 2021). "Furthermore, increased expression of OCT4 target gene NAIP/BIRC5 has been associated with therapeutic resistance in various human cancers." (PMID 33339129, 2020). "Thus, the −260/−1 region of the Survivin/BIRC5 promoter fully recapitulates the behaviour of the encoded gene in cancer cell lines." (PMID 32152425, 2020). "An alternative explanation could be the presence of mutated transcription factors’ binding sites along the BIRC5 promoter in cancer cells, which might affect the overall binding of the various transcriptional regulators, including YY1." (PMID 32899428, 2020). "In addition, the expression level of BIRC5 is found to be associated with tumorigenesis in cancer progression." (PMID 29459674, 2018).
cancer (continued). "Moreover, BIRC5 expression in cancer cells has been linked to tumour angiogenesis and inhibition of BIRC5 expression in tumour cells decreased tumour angiogenesis." (PMID 19788758, 2009). "BIRC5 is a member of apoptosis inhibitor family, its overexpression is related with the occurrence and progression of multiple cancer types and is significantly associated with worse overall survival and increased mortality in a variety of cancers, including ACC." (PMID 38053725, 2023). "Thus, SURVIVIN/BIRC5 overexpression has been associated with the onset and progression of several types of cancer, and, regarding HCC, the expression of SURVIVIN/BIRC5 has been reported in 41% of cases and its high expression has been associated with a poor prognosis in patients." (PMID 36499327, 2022). "On the other hand, the high expression of BIRC5 is very important, given that the BIRC5 gene encodes survivin protein, which is widely known for its antiapoptotic effect, association with resistance to cancer drug treatment, or as has been seen in resistance to PDT." (PMID 32397263, 2020). "Another notable example was CKAP2L, which clusters together with several genes identified from referencing of our immunopeptidomics data, including BIRC5, BRCA2, and CENPF, forming a cluster of genes associated with cell proliferation across cancers." (PMID 41477871, 2026). "Increased expression of BIRC5, or survivin, can prevent cells from dying and endow them with the capacity to develop into cancer." (PMID 39764737, 2025). "Our study confirms that high expression of BIRC5 is significantly associated with poor prognosis in ACC patients, consistent with its role in promoting metastasis and apoptosis resistance in other cancer types." (PMID 41244050, 2025). "These traits demonstrate BIRC5's value as a biomarker and its potential as a cancer treatment target." (PMID 40471223, 2025). "Our in vitro experiments showed that knocking down BIRC5 increased NK cell numbers and proliferation but reduced their immune function and cytotoxicity, potentially facilitating cancer cell growth." (PMID 39859485, 2025). "BIRC5, also known as Survivin, is a popular target for cancer treatment, and it is found to be the fourth most upregulated mRNA in the human cancer transcriptome." (PMID 40405133, 2025). "A subsequent analysis of BIRC5 expression according to tumor stages revealed significant variation in its expression throughout cancer progression (F = 6.27, p < 0.001)." (PMID 40725442, 2025). "On this basis, several selective inhibitors of BIRC5 (a regulator of autophagy) have been generalized to manage cancer by disrupting BIRC5′s homodimerization or interaction with partner proteins." (PMID 38276004, 2024). "Compared with previous studies, this study not only verified the overexpression of BIRC5 in various cancers but also expanded the understanding of its clinical significance." (PMID 39703228, 2024). "Future work should focus on the role of BIRC5 in immune escape mechanisms, assess its viability as a target for cancer therapies, and evaluate treatment strategies in clinical trials." (PMID 39703228, 2024). "The most commonly overexpressed genes in rare cancers included BIRC5 (88%), TOP2A (85%), CDK4 (82%), BRIP1 (76%), MSH6 (66%), and HDAC2 (62%)." (PMID 38347552, 2024). "Functional enrichment analysis suggested that BIRC5 shares similar roles across various cancers, further supporting its involvement in key cancer pathways." (PMID 39703228, 2024). "The study’s findings demonstrated that FMT restored the bacteria’s abundance in CRC mice to levels comparable to those in control mice, perhaps assisting in the downregulation of BIRC5 expression in cancer treatment-related scenarios." (PMID 39619695, 2024).
cancer (continued). "Several studies have shown that the BIRC5 protein is an inhibitor of apoptosis and is overexpressed in human cancer cells." (PMID 39453212, 2024). "The correlation between BIRC5 expression and key molecular and immune subtypes, along with its interaction with critical proteins involved in cancer-related pathways, underscores its role in tumorigenesis." (PMID 39703228, 2024). "The innovation of this study lies in its pan-cancer analysis, which not only confirmed the overexpression of BIRC5 across multiple cancers but also explored its potential role in tumor immune evasion." (PMID 39703228, 2024). "We conducted a survival analysis (OS, DSS, and PFI) across multiple cancer types based on BIRC5 expression." (PMID 39703228, 2024). "Propionate, produced by bacteria from Roseburia, Bacteroides, and Lachnospiraceae, inhibits cancer progression by inducing apoptosis and cell cycle arrest through down-regulating BIRC5 expression." (PMID 39619695, 2024). "Given the critical role of survivin (BIRC5) in tumor cell regulation, developing novel inhibitors represents a promising approach for cancer therapy." (PMID 39397921, 2024). "Although ROC curves are commonly used to assess diagnostic capability, in this context, they provide insights into the broader relevance of BIRC5 in differentiating cancerous tissues and its potential role in prognosis across various cancer types." (PMID 39703228, 2024). "The results from the heatmap analysis of BIRC5 expression and immune cell infiltration across various cancers indicated that BIRC5 exhibits immunosuppressive effects in many tumor types." (PMID 39703228, 2024). "The PPI network analysis identified key interacting proteins involved in the cell cycle and tumor progression, further supporting BIRC5's role in cancer biology." (PMID 39703228, 2024). "This highlights the importance of considering both mRNA and protein expression levels in understanding the role of BIRC5 in cancer progression." (PMID 39703228, 2024). "BIRC5 (Survivin) is a crucial anti-apoptotic protein overexpressed in various cancers, promoting tumor growth and treatment resistance." (PMID 39703228, 2024). "Survival of the cancer cells is optimized through the up-regulation of several key genes, ensuring evading apoptosis such are BIRC5 (x(T) = 6.04) and DDB2 (x(T) = 2.37)." (PMID 38790250, 2024). "Further analysis of BIRC5 expression in various cancer and normal cell lines through the BioGPS database indicated that BIRC5 was highly expressed in multiple cancer cell lines, whereas its expression was low in normal cell lines." (PMID 39703228, 2024). "GO analysis shows BIRC5’s involvement in regulating the cell cycle, cell division, and chromosome separation, consistent with its role in promoting cancer cell proliferation by inhibiting apoptosis." (PMID 39703228, 2024). "BIRC5 was significantly overexpressed in tumor tissues across 33 cancer types, with higher expression levels observed in tumors compared to normal tissues." (PMID 39703228, 2024). "These pathways and protein interactions provide a clearer picture of the mechanisms by which BIRC5 promotes cancer progression." (PMID 39703228, 2024). "Considering BIRC5’s high expression levels and poor prognostic implications, it holds promise as a marker for cancer diagnosis and prognosis." (PMID 39703228, 2024). "The aim of this study is to comprehensively analyze the expression patterns of BIRC5 across different cancer types using bioinformatics tools and databases." (PMID 39703228, 2024). "The findings reveal that BIRC5 is actively involved in key processes such as cell cycle regulation, nuclear division, and chromosome separation, all of which contribute to cancer progression." (PMID 39703228, 2024). "This study provides a comprehensive analysis of the expression patterns and clinical relevance of BIRC5 across a wide range of cancers." (PMID 39703228, 2024).
cancer (continued). "To examine the relationship between cancer development and BIRC5 and BIRC7, we compared the expression levels in patients at various stages." (PMID 38203388, 2023). "In this work, we used a PPRH directed toward the promoter sequence of survivin (BIRC5), an antiapoptotic gene overexpressed in many cancers, which produces a high degree of cytotoxicity due to an increase in apoptosis." (PMID 36839742, 2023). "In this study, we found a positive correlation between the expression of UBE2C and PLK1/BIRC5 in the Cancer Genome Atlas (TCGA) database, revealing a potential combination therapy candidate for pan-cancer." (PMID 37958642, 2023). "The primary clinical interest in BIRC5 is as a targeted cancer therapy, as it is the fourth most upregulated mRNA in the human cancer transcriptome." (PMID 37958642, 2023). "It has been shown that Birc5 is a poor prognostic marker of HCC by promoting cancer cell proliferation, inducing angiogenesis, and attenuating the sensitivity of tumor cells to radiotherapy and chemotherapy." (PMID 37326143, 2023). "Thereby, BIRC5 should be regarded as a potential target for anti-cancer drugs and prognosis prediction." (PMID 37679418, 2023). "The role of BIRC5 in tumor growth and development has also been identified in other cancers, including lung, brain and colon." (PMID 37077837, 2023). "When we analysed the cancer-specific genes like Cdc20, Hmmr, Tpx2, Cenpf, Birc5, Ube2c, Foxm1,Pold4, Nup210, Cenpm and Orc1, these pro-carcinogenic genes found to be over expressed in the disease control group." (PMID 36650455, 2023). "The lentiviral CRISPR/Cas9 nickase in these cancer cells led to BIRC5 gene editing, which resulted in the inhibition of EMT by upregulating epithelial cell markers and downregulating mesenchymal markers in both ovarian cancer cells." (PMID 37108214, 2023). "Numerous studies have shown that the elevation of BIRC5 induced multi-drug resistance in various cancers." (PMID 37834111, 2023). "As a well-known cancer therapeutic target, BIRC5 has been extensively researched, providing new insight into immunotherapy." (PMID 37741993, 2023). "This was further evaluated for the oncogene BIRC5, which was proposed for targeted treatment (BIRC5i) of various cancers including HRN." (PMID 37246217, 2023). "Various studies have shown that the cell-cycle-related regulatory proteins UBE2C, PLK1, and BIRC5 promote cell proliferation and migration in different types of cancer." (PMID 37958642, 2023). "Survivin (or BIRC5) is an anti-apoptotic protein that inhibits caspase activation and is highly expressed in most cancers, including GBM." (PMID 37111620, 2023). "BIRC5 (also known as Survivin) is an apoptosis inhibitory protein that exerts a role in inhibiting cell death and promoting cancer cell survival." (PMID 35880695, 2023). "We used a computational analysis and identified the BIRC5/HIF1A/FLT4 oncogenes as being highly upregulated in NSCLC and associated with cancer progression and poor prognoses." (PMID 37509650, 2023). "The data described in the present study showed that the combined inhibition UBE2C and PLK1 or BIRC5 caused a decrease in the mRNA expression of ACLY, suggesting a possible novel strategy for cancer therapy." (PMID 37958642, 2023). "The induction of apoptosis via inhibition of BIRC5 is a promising target for the treatment of various cancers." (PMID 38203388, 2023). "BIRC5 is significantly upregulated in most tumors, and its dysregulation affects cancer aggressiveness, recurrence, drug resistance, and patient survival." (PMID 38203388, 2023). "Co-suppression of OCT4 and BIRC5 can inhibit cancer proliferation by inducing cancer cell apoptosis and cell cycle arrest in HCC57." (PMID 37679418, 2023). "This is particularly important as Birc5-targeting compounds such as YM155 have advanced into numerous different human cancer clinical trials." (PMID 35836253, 2022).
cancer (continued). "The LC-LK CCPs are made of two or three nodes maximum and identified four genes (SNRK, BIRC5, HBB, and IL33) associated with the acquisition of the hallmarks of cancer." (PMID 36101460, 2022). "The other study found that BIRC5 influences the mitosis, apoptosis, and autophagy of the cancer cells." (PMID 36292719, 2022). "BIRC5 directly regulates apoptosis and mitosis in cancer cells during tumorigenesis and tumor metastasis." (PMID 35456460, 2022). "Treatment targeting BIRC5 has come to be recognized as a promising therapeutic approach due to the high activation of BIRC5 during carcinogenesis in various cancer types." (PMID 36358602, 2022). "Emerging evidence has demonstrated that baculoviral inhibitor of apoptosis repeat containing 5 (BIRC5) plays a critical role in cell apoptosis and the progression of diverse cancers." (PMID 35309512, 2022). "BIRC5 is a member of the apoptosis inhibitor gene family, which regulates several cancers by activating cell apoptosis process." (PMID 35664691, 2022). "For all analyzed cancer types, BIRC5 levels were shown to be significantly higher in cancer tissue than corresponding normal tissues." (PMID 35331169, 2022). "BIRC5 has been demonstrated to act as an oncogene to modulate the growth, migration and invasion of various cancer cells." (PMID 35322532, 2022). "ReactomeFIViz enrichment analysis in Cytoscape showed that four genes (SNRK, BIRC5, HBB, and IL33) have evidence of their association with the acquisition of cancer characteristics." (PMID 36101460, 2022). "Treatment that targets BIRC5 has been recognized as a unique approach for numerous malignant tumors since BIRC5 is typically overexpressed in many malignancies." (PMID 36358602, 2022). "To understand the expression pattern of BIRC5 in cancers, we obtained the expression profile of BIRC5 in 33 different tumors provided in the cancer genome atlas (TCGA) database and matching normal sample types from GETx database using GEPIA." (PMID 35886952, 2022). "Since BIRC5 is frequently up-regulated in diverse cancers and treatment that targets BIRC5 has been increasingly noticed as a novel strategy for various malignant tumors." (PMID 35309512, 2022). "In our investigation, we chose sphingolipid metabolic genes for pan-cancer analysis, and the findings indicated that the BIRC5 protein was expressed at a high level in most of the malignancies, consistent with earlier research." (PMID 36518255, 2022). "Birc5 (Baculoviral IAP Repeat Containing 5, also known as survivin) acts at the crossroads of multiple cancer pathways, which include regulations of mitosis and apoptosis." (PMID 35836253, 2022). "In conclusion, BIRC5 is indeed overexpressed in most cancer types, which frequently correlates with patient clinical outcome." (PMID 35331169, 2022). "Treatment targeting BIRC5 has been recognized as a unique approach for numerous malignant tumors because BIRC5 is typically overexpressed in most cancers." (PMID 36358602, 2022). "Given that BIRC5 was found to be highly expressed in diverse cancer types, we used the kmplot database to examine the prognostic value of BIRC5 across human cancers." (PMID 35309512, 2022). "A limitation of the current study was the lack of large datasets similar to the TCGA dataset that contained both gene expression and clinical data to validate the prognostic relevance of BIRC5 expression in cancer." (PMID 35331169, 2022). "According to several studies, high BIRC5 expression is positively correlated with a worse prognosis for survival and relapse from various cancer types." (PMID 36358602, 2022). "Many cancers commonly express more BIRC5, which has been correlated to chemoresistance and a bad prognosis for cancer patients, which is consistent with our findings." (PMID 36358602, 2022).